MPO (myeloperoxidase)
Diseases named in the same sentence as MPO in open-access papers (continued):
Sharing a sentence is not in itself a finding about the gene and the disease.
lung carcinoma (continued). "Our data strongly suggest that MPO is an enzyme that promotes cancer cell growth and could be used as a target for lung cancer treatment." (PMID 37627581, 2023). "Indeed, MPO inhibition resulted in a 50% reduction in tumour burden in a mouse model of lung carcinoma." (PMID 37699574, 2023). "We showed that MPO activity is involved in altering lung cancer cell function in vitro." (PMID 37627581, 2023). "To further understand the role of MPO in the setting of lung cancer, we aimed to investigate whether MPO can alter the function of tumour cells in vitro." (PMID 37627581, 2023). "MPO found in the lungs may contribute to lung cancer by activating harmful substances, including aromatic amines." (PMID 37513924, 2023). "The purpose of the current study was to determine the role of MPO in lung cancer cells." (PMID 37627581, 2023). "Moreover, S100A8 can induce the activation of MPO, and novel monoclonal antibody against it efficiently prevents lung cancer metastasis." (PMID 34993203, 2021). "Interestingly, a prior study reported that, in a toxin-induced lung cancer model, MPO inhibition decreased tumor multiplicity." (PMID 34944979, 2021). "It had been demonstrated that High MPO+ cell infiltration in colorectal cancer was an independent favorable prognostic factor and MPO inhibitor reduced lung carcinoma growth during the early stages of tumor progression, suggesting that MPO+ neutrophil involved promoting lung cancer growth." (PMID 27446967, 2016). "Furthermore, patients suffering from COPD and lung cancer exhibit increased levels of MPO in serum and BALF." (PMID 24821130, 2014). "Our studies advocate for the use of MPO inhibitors in a lung cancer prevention setting." (PMID 24821130, 2014). "However, BAL fluid and serum levels of both NE and MPO were significantly higher in patients with lung cancer than COPD patients or healthy individuals (P < 0.05)." (PMID 23919722, 2013). "However, serum NE and MPO levels were significantly higher in patients with advanced lung cancer than in those with early lung cancer (P < 0.05)." (PMID 23919722, 2013). "In addition, we provided evidence that intracellular ROS was increased in peripheral blood neutrophils of lung cancer patients which positively correlated with levels of both inflammatory markers (NE, MPO)." (PMID 23919722, 2013). "Furthermore, elevated levels of myeloperoxidase (MPO)-DNA complexes, markers of NETosis, were observed in lung cancer patients and correlated with C5a levels, suggesting that C5a promotes NET formation and potentially facilitates cancer dissemination and metastasis." (PMID 41300283, 2025). "The cumulative result provided a more powerful evidence and we intended to draw a conclusion that MPO-463G > A polymorphism may not be a good predictor of lung cancer both in Caucasians or Asians." (PMID 28764808, 2017). "Therefore, we hypothesized that MPO is a target for prevention of lung cancer and investigated its role in animal models of lung tumor development." (PMID 24821130, 2014). "In summary, our meta-analysis suggests that the MPO −463G>A polymorphism may not be a risk factor for lung cancer." (PMID 23840365, 2013). "In addition, there is evidence of MPO role in pathogenesis of lung cancer." (PMID 23919722, 2013). "Thus, our findings let us hypothesize that in patients with lung cancer neutrophils appear in a more activated state through the production of NE, MPO than in patients with COPD." (PMID 23919722, 2013). "For example, inhibiting MPO chlorination reduces levels of hypochlorous acid (HOCI, the main oxidation product of MPO in vivo), which can induce apoptosis in A549 lung cancer cells." (PMID 39759427, 2025). "Among the most interesting studies conducted in the last 10 years, CancerSEEK reported a panel of eight proteins (CA-125, CEA, HGF, Myeloperoxidase, OPN, Prolactin, and TIMP-1) effective in distinguishing lung cancer patients from healthy controls." (PMID 38068296, 2023).
lung carcinoma (continued). "In our study, we observed increased levels of MPO in the lungs of BHT-treated mice, consistent with that observed in COPD and lung cancer patients." (PMID 24821130, 2014). "Although we demonstrated that neutrophil cell count and percentage in BAL fluid were lower in lung cancer groups compared with COPD patients, NE and MPO levels in BAL fluid were significantly higher in lung cancer groups than in COPD group." (PMID 23919722, 2013). "Other MPO inhibitors (e.g., AZD3241, AZD4831, SNT-8370, UFM24) have been investigated for their anti-inflammatory effects in neutrophilic lung injury, but their roles in lung cancer treatment warrant further exploration." (PMID 41254689, 2025). "Additionally, when stimulated with PMA, a NET activator, neutrophils from patients with lung cancer underwent significantly exaggerated NET release compared with healthy controls, as demonstrated by the increased amount of extracellular MPO–DNA complex." (PMID 35036439, 2022). "The data showed that smokers with combined MPO genotype had a lower lung cancer prevalence than nonsmokers." (PMID 35227278, 2022). "We observed that mean serum and BAL fluid levels of NE and MPO were significantly higher in patients with lung cancer (with or without COPD) compared with COPD patients and healthy subjects." (PMID 23919722, 2013). "Nevertheless, there are no clear data comparing the importance of NE and MPO in lung cancer and COPD." (PMID 23919722, 2013). "Our data do not support proposed associations between lung cancer and EPHX1 rs2234922, CYP1B1 rs1800440, and MPO rs2333227." (PMID 19479063, 2009). "Inflammatory cells, such as those found in the lung cancer studies by Thannickal and more recently by Aggarwal and collaborators, produce more ROS by inducing oxidant-generating enzymes, such as NADPH oxidase, iNOS, xanthine oxidase (XO), and myeloperoxidase (MPO)." (PMID 36765772, 2023). "Indeed, in the lung cancer study, the authors found that inhibiting the MPO activity did not have an effect on implanted tumors, suggesting that MPO activity has a role in the early phase of cancer development." (PMID 34944979, 2021). "Patients at increased risk of lung cancer, such as those with COPD, may benefit from prophylactic treatment with non-toxic MPO inhibitors to reduce chances of developing lung cancer." (PMID 24821130, 2014). "However, serum and BAL fluid NE and MPO levels did not significantly differ in lung cancer groups (with and without COPD) (P > 0.05)." (PMID 23919722, 2013). "Furthermore, our findings of higher systemical NE, MPO and ROS production in patients with early lung cancer compared with COPD patients further support the fact, that chronic inflammation can be more pronounced in lung cancer than COPD." (PMID 23919722, 2013). "Therefore, the aim of our study was to evaluate the local and systemic chronic inflammation by investigating the amount of neutrophils and markers of their activity (ROS, NE, MPO) in peripheral blood and BAL fluid of patients with lung cancer, COPD and having both diseases simultaneously." (PMID 23919722, 2013). "We analyzed 25 SNPs (some previously untested) in 2101 primary lung cancer cases and 2120 population controls from the Environment And Genetics in Lung cancer Etiology (EAGLE) study from six phase I metabolic genes, including cytochrome P450s, microsomal epoxide hydrolase, and myeloperoxidase." (PMID 19479063, 2009). "Twenty-two malignancies were observed in 20 patients (20/240, 8.3%; 11 c-ANCA/PR3 ( +), 3 in p-ANCA/MPO ( +), and 2 in ANCA negative patients), which were 3 carcinomas of the lung, 7 genitourinary tract, 5 hematological system, 3 thyroid papillary, 2 breast, 1 sarcoma and 1 oral cavity." (PMID 40332571, 2025).
lung carcinoma (continued). "Although there is no direct evidence that TANs and TAM interact via MPO and MMR, there is already evidence that a large MPO-positive neutrophil infiltrate is found in colorectal and lung cancers, with high levels of macrophage mannose receptor (MMR) expression by M2-like macrophages." (PMID 40160822, 2025).
Alzheimer disease (41 papers, 2013 to 2026). A progressive, neurodegenerative disease characterized by loss of function and death of nerve cells in several areas of the brain leading to loss of cognitive function such as memory and language. "It was recently shown that cognitive, memory, and proinflammatory activities were improved in the Alzheimer’s disease mouse model (5XFAD) after producing bone marrow deficient MPO." (PMID 38473707, 2024). "In a murine model of Alzheimer’s disease, MPO deficiency resulted in significantly reduced levels of inflammatory mediators in the hippocampus and this was correlated with superior performance in spatial learning and memory." (PMID 38673843, 2024). "Sex-specific risk for Alzheimer’s disease among individuals with the MPO GG genotype also has been reported." (PMID 36873953, 2023). "Of the studies reporting an association between mutation in α2M and risk of Alzheimer's disease, one study has reported that there is a synergistic effect between polymorphisms in α2M and myeloperoxidase and an increased risk of Alzheimer's disease." (PMID 31428227, 2019). "The objective of this study was to explore the genetic association of myeloperoxidase (MPO) gene polymorphisms with risk of Alzheimer's disease (AD)." (PMID 29296208, 2017). "Several previous studies indicated that after morphine exposure, the activity of SOD and CAT enzymes was decreased, Additionally, MPO has been linked to neurological diseases, with significantly higher peripheral blood concentrations observed in Alzheimer's disease patients." (PMID 41404029, 2025). "However, this also represents a key strength of the study, as we are the first to investigate serum PON3 in the context of Alzheimer’s disease and its association with MPO." (PMID 39456469, 2024). "In addition to neutrophils, microglia and pyramidal neurons of the hippocampus also express a substantial amount of MPO enzyme, which is associated with disease conditions such as Alzheimer’s disease and multiple sclerosis." (PMID 36675440, 2023). "In addition, they inhibit the expression of inflammatory genes associated with Alzheimer’s disease such as IL1b (interleukin 1β) and Mpo (myeloperoxidase) in rat models of the disease." (PMID 36440293, 2022). "In a study about how MPO and microglia play a role in neurodegenerative Alzheimer’s disease, researchers found that MPO could cause the production of ROS and TNFα, the leading proinflammatory cytokines in this disease, in and around microglia, inducing neuronal apoptosis and necrosis." (PMID 38275657, 2024). "Myeloperoxidase (MPO) plays a role in the development of neurodegenerative diseases such as Alzheimer’s disease." (PMID 39950933, 2025). "Then, this review highlights the role of myeloperoxidase (MPO) in Alzheimer’s disease (AD), linking it to oxidative damage and neuroinflammation through the production of hypochlorous acid (HOCl)." (PMID 39950933, 2025). "As a result, the evaluation of antioxidant molecules for Alzheimer’s disease (AD) that also inhibit MPO has been suggested." (PMID 39950933, 2025). "In the context of aging-related brain injury, pre-clinical studies have been describing the role of myeloperoxidase (MPO) in neurodegenerative diseases, such as Alzheimer's disease, Parkinson's disease, and multiple sclerosis." (PMID 37150212, 2023). "Many studies have found increased plasma MPO in patients with Alzheimer’s disease with co-localized MPO in beta-amyloid plaques." (PMID 38004170, 2023). "Third, myeloperoxidase, encoded by MPO, an MD gene, is expressed in the astrocytes of the Alzheimer’s disease brain where it supports the oxidation of phospholipids." (PMID 36771351, 2023). "MPO has been proposed as a biomarker and important therapeutic target in various neurodegenerative diseases, including multiple sclerosis, Alzheimer's disease, and Parkinson's disease." (PMID 35178161, 2022).
Alzheimer disease (continued). "Although the reasons for this are unclear, myeloperoxidase-immunoreactivity is also detected in neurons in Alzheimer's disease." (PMID 31428227, 2019). "We studied the cellular localization of MPO and compared numbers of MPO cells in various brain regions between neurologically healthy individuals and patients with Parkinson’s disease (PD) or Alzheimer’s disease (AD; n = 10–25)." (PMID 28466093, 2017). "It has been reported that some chest pain patients show significant MPO levels and MPO oxidation products have been observed in brains of patients diagnosed with Alzheimer’s disease and multiple sclerosis." (PMID 25168993, 2014). "Elevated expression of MPO has previously been demonstrated in chronic neurological disease states, such as Alzheimer's disease, Parkinson's disease, multiple sclerosis, and autism spectrum disorder." (PMID 24069051, 2013). "The signature supports the role of APOE in lipid regulation through apolipoproteins and inflammation and includes, among others, neutrophil secreted granule proteins CAMP, CTSG, DEFA3, and MPO that point to inhibition of OLFM4 as a target for Alzheimer's disease therapeutics." (PMID 41316897, 2026). "The MPO GG genotype (increasing production of myeloperoxidase) was associated with a higher risk for Alzheimer’s disease among Caucasians but not Hispanics." (PMID 36873953, 2023). "Furthermore, the activity of plasma MPO is a supposed biomarker of several cardiac scenarios and neurodegenerative disorders like Alzheimer's disease." (PMID 35178161, 2022). "Additionally, MPO promotes cognitive impairment in murine models of Alzheimer’s disease, as MPO KO animals showed improved performance in behavioral, learning and memory assessments." (PMID 36293108, 2022). "Indeed, it is found that neutrophils drive an increase in MPO in the brain in Alzheimer’s disease (AD), through their accumulation in the vasculature and the formation of neutrophil extracellular traps, providing a peripheral target." (PMID 35453292, 2022). "Likewise, neurons from patients with Alzheimer’s Disease (AD) expressed increased MPO levels and MPO is co-localized with amyloid-b protein, which is crucially involved in AD." (PMID 33916434, 2021). "While a profound body of evidence associates neutrophil-derived MPO in the pathogenesis of Alzheimer’s disease (AD), this role has not been assessed in an animal model of AD." (PMID 31611761, 2019). "On the other hand, astrocyte-specific overexpression of human MPO in an Alzheimer’s disease mouse model resulted in cognitive decline, accumulation of the lipid peroxidation product 4-hydroxynonenal along with the formation of phospholipid- and plasmalogen-derived hydro(pero)xides." (PMID 23691142, 2013). "A recent study suggested that neutrophils and neutrophil extracellular traps are key sources of MPO in the brain during Alzheimer's Disease (AD), which may represent an important mechanism through which blood brain barrier inflammation influences oxidative stress in AD." (PMID 37150212, 2023). "MPO may also play a role in neurologic diseases such as Parkinson’s and Alzheimer’s dementia." (PMID 38004170, 2023). "This extended signature includes granule proteins CAMP, CTSG, DEFA3, and MPO secreted from neutrophils and points to olfactomedin 4 (OLFM4) as a new target for the prevention of Alzheimer's disease." (PMID 41316897, 2026). "Research has also reported increased MPO in MDD, neurodegenerative disorders including Alzheimer's Disease, and preclinical PTSD." (PMID 37333909, 2023). "In the healthy brain, neurons do not normally express MPO, although neuronal expression of MPO has been detected in Alzheimer's disease." (PMID 23401848, 2013).
pancreatitis (41 papers, 2006 to 2026). Inflammation of the pancreas. "In this study, the data showed that BA attenuated the severity of AP, as indicated by the reduced levels of amylase and lipase, MPO activity, inflammatory cytokines, and pancreatitis-associated lung injury." (PMID 34206763, 2021). "Sodium taurocholate-induced pancreatitis-associated ALI was associated with an increase in lung MPO activity at 3, 6, 12, and 24 h." (PMID 29359164, 2017). "Injury to acinar cells in pancreatitis causes release of cytokines and recruits neutrophils which can be measured as an increase in tissue myeloperoxidase (MPO) activity." (PMID 16700916, 2006). "In pancreatitis-induced lung injury, apigenin was associated with decreased TNF-α, IL-6, and MPO expression, indicating attenuation of both cytokine-mediated and oxidative damage." (PMID 40429525, 2025). "Lung MPO measurements showed a decrease resulting from TLCS or LCA in caerulein-induced pancreatitis, indicating collateral attenuation of extra-pancreatic damage, and local pancreatic damage was decreased after the addition of these hydrophobic BAs, as well." (PMID 36362379, 2022). "Measurements in lung tissue homogenate confirmed pancreatitis-induced elevated myeloperoxidase activities, which were significantly reduced in both antibody treatment groups compared to the isotype controls." (PMID 36300116, 2022). "Our results revealed that pre- and post-treatment with BA significantly reduced the severity of pancreatitis, as evidenced by a decrease in histological damage in the pancreas and lung, serum amylase and lipase activity and pancreatic myeloperoxidase activity." (PMID 34206763, 2021). "In rats with L-arginine-induced pancreatitis, lycopene treatment reduced tumor necrosis factor-α, myeloperoxidase activity, and inducible nitric oxide synthase gene expression." (PMID 33672594, 2021). "The serum levels of amylase, lipase, and MPO, the most commonly used biochemical markers for pancreatitis, were also significantly reduced in the ANGPTL4−/− mice." (PMID 32638512, 2020). "Serum amylase, pancreas trypsin activity, and pancreas myeloperoxidase activity were significantly increased in the high-iron diet group, indicating that high iron levels accelerate pancreatitis progress." (PMID 33311482, 2020). "Neutrophils were recruited into the injured pancreases during pancreatitis progression, whereas notably fewer MPO+ cells were observed in the injured pancreases from caerulein-AP mice pretreated with polyI:C." (PMID 31130960, 2019). "Pancreatitis was markedly reduced in Piezo1aci KO mice as indicated by reductions in edema, MPO measurements, and histological parameters." (PMID 29712913, 2018). "In the model of L-arginine-induced pancreatitis, lung MPO activity was increased 72 h after induction, corroborating previous findings." (PMID 29861777, 2018). "Treatment with SSBE decreased the lung MPO activity after the induction of pancreatitis at 12 and 24 h (p < 0.05)." (PMID 29359164, 2017). "HTRA1 protein expression and the number of MPO-positive cells both significantly increased in the pancreatic tissue of rat pancreatitis compared with those in the control group, and this effect was decreased by emodin at a dose of 60 mg·kg−1." (PMID 29163548, 2017). "The severity of pancreatitis was evaluated by serum amylase activity, pathological scores, myeloperoxidase activity, and the expression of inflammation factors in pancreas." (PMID 27302647, 2016). "Our results demonstrated that administration of diazepam (5 mg/kg i.p.)reduced amylase and lipase activity, TNF-alpha, MPO activity, and pathological alterations, which are markers of pancreatitis." (PMID 23956866, 2013). "Biochemical and immunological assays confirmed that administration of EAE reduced amylase and lipase activity, TNF-alpha, IL-6, MPO activity, and lipid peroxidation which are markers of pancreatitis." (PMID 23008778, 2012).